TACSTD2 (tumor associated calcium signal transducer 2)
Diseases named in the same sentence as TACSTD2 in open-access papers (continued):
Sharing a sentence is not in itself a finding about the gene and the disease.
gastric cancer (43 papers, 2011 to 2025). A primary or metastatic malignant neoplasm involving the stomach. "TACSTD2 has been found associated with tumor aggressiveness and poor prognosis in epithelial cell tumors, including colon and stomach cancer." (PMID 21347233, 2011). "TACSTD2 functions as an intracellular calcium signal transducer and is generally overexpressed in epithelial cancers such as pancreatic and gastric carcinoma." (PMID 29538454, 2018).
bladder cancer (37 papers, 2017 to 2026). "The tumor-associated calcium signaling 2 (TACSTD2) protein, which exhibits potential in the detection of bladder cancer, is one of the 29 urine exosomal proteins that have emerged as novel prospective biomarkers." (PMID 40612948, 2025). "In another study, mass spectrometry and ELISA were used to establish the association of tumor-associated calcium-signal transducer 2 (TACSTD2) with bladder cancer in urinary exosomes." (PMID 39001524, 2024). "The great potential of TACSTD2 as a diagnostic biomarker for bladder cancer was further supported by the validation of another cohort of study and by the fact that it was exclusively made by cancer cells." (PMID 35757760, 2022). "Our study revealed a strong association of TACSTD2 with bladder cancer and highlighted the potential of human urinary microparticles in the noninvasive diagnosis of bladder cancer." (PMID 28851367, 2017). "Tumor-associated calcium-signal transducer 2 (TACSTD2) is highly expressed in uEVs of patients with bladder cancer and was proposed as a biomarker." (PMID 28638822, 2017). "We quantified cancer-associated calcium-signal transducer 2 (TACSTD2) in raw urine specimens using a commercial ELISA and confirmed its potential value for diagnosis of bladder cancer." (PMID 28851367, 2017). "In addition, tumor-associated calcium-signal transducer 2 (TACSTD2) was seen as a candidate biomarker for bladder cancer." (PMID 30769831, 2019). "about a potential biomarker TACSTD2 for bladder cancer, which was significantly increased in urinary exosomes of patients compared to individuals with hernia." (PMID 35757760, 2022). "Finally, a proteomic analysis identified 2964 proteins in the urine exosomes of 28 bladder cancer patients, revealing that exosomal trophoblast cell surface antigen 2 (TACSTD2) was significantly higher in the patients’ urine than in individuals with hernias." (PMID 36834471, 2023). "Moreover, they found that concentrations of TACSTD2 in urinary exosomes had 6.5-fold higher expression in bladder cancer patients compared to control patients, which has high potential as a novel biomarker for early diagnosis and prognosis for bladder cancer." (PMID 36203422, 2022). "Twenty-nine urinary exosomal proteins have emerged as novel candidate biomarkers, especially tumor-associated calcium-signal transducer 2 (TACSTD2), which was directly quantified by ELISA in urine specimens and confirmed to have potential value for diagnosis of bladder cancer." (PMID 29282096, 2017).
colorectal cancer (30 papers, 2011 to 2026). A primary or metastatic malignant neoplasm that affects the colon or rectum. "The role of TACSTD2 gene in progression and aggressiveness of colorectal cancer has been confirmed in different studies, but coincidence of colorectal cancer in patients with GDLD has been less considered." (PMID 29988226, 2017). "TACSTD2 was identified as an oncogene in colorectal cancer cells." (PMID 22053771, 2011). "Thus, we aimed to analyse whether TACSTD2 expression might be silenced by promoter methylation in colorectal cancer and further explored if binding of the active H3K4me3 code could facilitate TACSTD2 gene transcription." (PMID 38302503, 2024). "In summary, our data suggest an inverse correlation between TACSTD2 promoter methylation and TROP2 expression in colorectal cancer in vitro and in vivo." (PMID 38302503, 2024). "However, the role of TACSTD2 promoter hypermethylation in colorectal cancer has not been investigated yet." (PMID 38302503, 2024). "TACSTD2 was proposed to be a Wnt target identified through consistent gene expression changes in APC-mutant intestinal adenomas from humans and mice; EFNB1 :Eph-related receptor is a Wnt signalling target gene in colorectal cancer that binds to the EFNB1 ligand." (PMID 27534621, 2016).
cervical carcinoma (28 papers, 2011 to 2026). A carcinoma arising from either the exocervical squamous epithelium or the endocervical glandular epithelium. "Specifically, 9 of the 13 tumor groups exhibited elevated TACSTD2, particularly for cervical cancer, colon cancer, esophageal carcinoma, liver cancer and thyroid carcinoma." (PMID 38698420, 2024). "Although Gal-7 affects the specific cervical cancer networks in different ways, we identified a group of eight molecules that are regulated in both cell lines: CRYAB, TACSTD2, BCL-3, COX19, OASL, CDKN2A/p14ARF, NIBAN/FAM129A, and FST." (PMID 27558259, 2016). "In published cell culture experiments, knockdown of TACSTD2 inhibits growth in MCF7 (contrary to our findings) and colon cancer cells, fetal rat lung cells (fibroblasts), fetal lung fibroblasts, cervical cancer cells, and laryngeal carcinoma cells." (PMID 30002602, 2018).
colon carcinoma (25 papers, 2008 to 2025). "Our data provide novel evidence for promoter demethylation and simultaneous gains of the active histone mark H3K4me3 across CpG-rich sequences, both being complementary mechanisms in the transcriptional regulation of TACSTD2 in colon cancer." (PMID 38302503, 2024). "In silico analysis of GSE156613 data set confirmed that a higher binding of histone mark H3K4me3 around the TACSTD2 promoter was found in TACSTD2 high expressing tumors of colon cancer patients compared to the corresponding adjacent tumor tissue." (PMID 38302503, 2024). "We found an inverse correlation between DNA methylation of the TACSTD2 promoter and TROP2 mRNA/protein expression in colon cancer cells and human colon cancer samples." (PMID 38302503, 2024). "In the present study, we add novel data about an inverse correlation between TACSTD2 promoter methylation and the active H3K4me3 epigenetic mark in colon cancer cell lines and patients' tumor tissue." (PMID 38302503, 2024). "Although not essential for cell proliferation under normal condition, ectopic expression of TACSTD2 enhances anchorage-independent cell growth, promotes tumorigenesis and metastasis in colon cancer cells." (PMID 22053771, 2011). "Thus, our data suggest that promoter demethylation and simultaneous gains of the active histone mark H3K4me3 across CpG-rich sequences are complementary mechanisms in the gene transcription regulation of TACSTD2 in colon cancer tissues." (PMID 38302503, 2024).
lymph node metastasis (23 papers, 2008 to 2026). "Multiplex immunohistochemistry (mIHC) staining of 4 MISs (CD44, S100A14, RHOD, and TACSTD2) in ESCC clinical samples demonstrated differential MIS expression scores (dMISs) predict lymph node metastasis, overall survival, and risk of carcinothrombosis." (PMID 38864342, 2024).
squamous cell carcinoma (23 papers, 2011 to 2025). A carcinoma arising from squamous epithelial cells. "Loss of TACSTD2 promoted squamous cell carcinoma progression and resistance through attenuating chemotherapeutic reagent-induced apoptosis, implying that TACSTD2 could be used as a marker for pathological grading of SCC." (PMID 33515271, 2021). "FGFR3, LYPD3, PVRL4, SDC1, and TACSTD2 exhibited significantly elevated expression levels in squamous cell carcinoma relative to adenocarcinoma." (PMID 40046734, 2025). "High expression of TACSTD2 in squamous-cell carcinoma, pancreatic, colorectal and gastric cancers have been associated with poor prognosis and higher incidence of metastasis and death." (PMID 22053771, 2011).
gelatinous drop-like corneal dystrophy (20 papers, 2007 to 2025). Gelatinous drop-like corneal dystrophy (GDCD) is a form of superficial corneal dystrophy characterized by multiple prominent milky-white gelatinous nodules beneath the corneal epithelium, and marked visual impairment. "Gelatinous drop-like corneal dystrophy (GDLD) is a rare autosomal recessive corneal dystrophy that has been associated with mutations in the TACSTD2 (M1S1) gene, which is normally expressed in corneal epithelial cells." (PMID 36875631, 2023). "The authors investigated bilateral GDLD corneal amyloidosis in two teenage girls (8 and 13 year) and showed a novel TACSTD2 mutation, c.653delA, occurred in both patients." (PMID 31534795, 2019). "In the current study, we conducted a mutation screening of tumor-associated calcium signal transducer 2 (TACSTD2) gene in six consanguineous Iranian families with gelatinous drop-like corneal dystrophy (GDLD), in order to find the causative mutations." (PMID 29988226, 2017). "Genomic alterations of the human TROP2 were shown to cause a rare genetic disease, whereby TACSTD2 mutations induce an amyloid corneal dystrophy (Gelatinous Drop-like Corneal Dystrophy, GDLD), while other organs that host Trop-2-expressing epithelia remain devoid of amyloid deposits." (PMID 37456256, 2023). "This study reports two novel mutations in 3 GDLD families and expands the spectrum of mutations in TACSTD2 that may cause pathological corneal amyloidosis." (PMID 21541270, 2011). "The newly identified mutation expands the spectrum of mutations in TACSTD2 that may cause pathological corneal amyloidosis." (PMID 19693293, 2009). "Congenital mutations in the human TACSTD2 gene cause a gelatinous drop-like corneal dystrophy (GDLD)." (PMID 33187148, 2020). "We identified a novel mutation of the tumor-associated calcium signal transducer 2 (TACSTD2) gene in a Japanese patient with gelatinous drop-like corneal dystrophy (GDLD)." (PMID 31666974, 2019). "In humans, congenital mutations of TACSTD2 cause a gelatinous drop-like corneal disease (GDLD), a rare autosomal recessive disease characterized by the development of bilateral corneal amyloidosis and eventually blindness." (PMID 35688908, 2022). "Similarly, TACSTD2, which encodes the TROP2 protein, is the causative gene for human gelatinous drop-like corneal dystrophy (GDLD), which causes photophobia and vision loss due to amyloid deposition under the corneal epithelium." (PMID 40705412, 2025).
endometrial cancer (19 papers, 2012 to 2026). Primary or metastatic malignant neoplasm involving the endometrium (mucous membrane that lines the endometrial cavity). "Interestingly, other studies have found highly expressed TACSTD2 in aggressive endometrial carcinomas associated with tumor invasion, and it has been suggested as an attractive target for cancer immunotherapy in biologically aggressive endometrial carcinomas." (PMID 34150764, 2021).
urothelial carcinoma (19 papers, 2021 to 2026). A malignant neoplasm derived from the transitional epithelium of the urinary tract (urinary bladder, ureter, urethra, or renal pelvis). "TROP2 (TACSTD2) expression is associated with decreased overall survival (OS) in some solid tumors, and the TROP2-targeting antibody-drug conjugate (ADC) sacituzumab govitecan has been approved in breast and urothelial carcinomas." (PMID 38986529, 2024). "For instance, in urothelial carcinoma, both NECTIN4 and Trop2/TACSTD2 are frequently overexpressed, and their expressions are closely linked." (PMID 38794221, 2024).
lung adenocarcinoma (17 papers, 2015 to 2025). A carcinoma that arises from the lung and is characterized by the presence of malignant glandular epithelial cells. "Hypermethylation and concurrent loss of TACSTD2 mRNA expression as a potential mark for epigenetic silencing has already been demonstrated for a number of human malignancies such as cholangiocarcinoma, lung adenocarcinoma, malignant glioma and HCC." (PMID 33882870, 2021). "Hypermethylation of TACSTD2 loci has been described in lung adenocarcinoma, HCC and cholangiocarcinoma." (PMID 33882870, 2021). "Low expression of Trop2 in lung adenocarcinomas was attributed to the DNA hypermethylation in the TACSTD2 promoter region or by the loss of heterozygosity." (PMID 33187148, 2020). "The only other epithelial cancer where TACSTD2 was found to be downregulated is lung adenocarcinoma." (PMID 29538454, 2018). "In contrast, an opposite behaviour has been described for TACSTD2 mRNA and/or protein expression in cancer tissues in lung adenocarcinoma, head and neck squamous cell cancer (HNSCC) and hepatocellular carcinoma (HCC) when compared to the non-tumoral counterpart." (PMID 33882870, 2021).
corneal dystrophy (14 papers, 2007 to 2024). The term corneal dystrophy embraces a heterogeneous group of bilateral genetically determined non-inflammatory corneal diseases that are usually restricted to the cornea. "Humans with pathological variants in TACSTD2 develop gelatinous drop-like corneal dystrophy, which is a degenerative disease of the cornea." (PMID 39666736, 2024). "Biallelic loss-of-function mutations in TACSTD2 are known to cause gelatinous drop-like corneal dystrophy, which suggests that the expression of this gene is functionally important only to the eye." (PMID 37835579, 2023). "Mutation in another retrogene, TACSTD2 — tumor associated calcium signal transducer 2, causes a gelatinous drop-like corneal dystrophy which leads to blindness." (PMID 32408516, 2020). "Mutations in the TACSTD2 gene result in gelatinous drop-like corneal dystrophy, an autosomal recessive disease that causes blindness due to amyloid deposition arising from the loss of epithelial barrier function." (PMID 29538454, 2018). "Mutation in another retrogene, TACSTD2 (tumor-associated calcium signal transducer 2) causes gelatinous drop-like corneal dystrophy, leading to blindness." (PMID 28406439, 2017). "Indeed, genetic defects in TACSTD2 cause a loss of TJ function in the cornea, leading to gelatinous drop-like corneal dystrophy." (PMID 29538454, 2018). "Studies of the genetic basis of the corneal dystrophies have revealed that most reported cases of gelatinous corneal dystrophy are caused by amino acid substitutions within the TACSTD2 gene, and most reported mutations have been missense and nonsense mutations." (PMID 17653040, 2007).
breast tumors (12 papers, 2011 to 2026). "TACSTD2-low breast tumors were enriched for copy number amplifications in CCND1 and FGF/R family member genes." (PMID 38986529, 2024). "Analysis of DNA methylation of TACSTD2 and protein expression of its product, trophoblast antigen protein 2 (TROP2), was extended to a panel of primary (n = 34) and recurrent (n = 34) breast tumors." (PMID 30002602, 2018). "The correlation coefficients in the normal breast tissue are 0.15, 0.06, 0.03 for the three CREB probes in the Affymetrix array, and the correlation coefficients in the breast tumor tissues are 0.46, 0.21, 0.31, respectively, suggesting CREB could regulate TACSTD2." (PMID 22053771, 2011).
head and neck squamous cell carcinoma (10 papers, 2015 to 2024). A squamous cell carcinoma that arises from any of the following anatomic sites: lip and oral cavity, nasal cavity, paranasal sinuses, pharynx, larynx, and salivary glands. "Moreover, TACSTD2 mRNA levels are decreased in a subset of primary head-and-neck squamous cell carcinomas with features of EMT." (PMID 33187148, 2020).
thyroid cancer (10 papers, 2017 to 2025). "TROP-2, also known as tumor-associated calcium signal transducer 2, is a 35 kDa, 323-amino-acid, type-1 transmembranous glycoprotein, and its overexpression is present in the majority of human carcinomas, including thyroid carcinoma, and can serve as a potential diagnostic marker for PTC." (PMID 34833464, 2021). "Concurrently, SERPINA1 and TACSTD2 show peak expression in tissue stem cell phases, suggesting their cooperative regulation of stem-like malignant properties in thyroid cancer." (PMID 40520228, 2025).
metastatic disease (9 papers, 2015 to 2025). "Moreover, the direct, but inverse, correlation interaction between GSE1 and TACSTD2 drives metastatic disease, castration resistance, and disease progression and modulates the clinical and immune statuses of patients with PCa." (PMID 34439112, 2021).
oral squamous cell carcinoma (9 papers, 2011 to 2025). "Additionally, TACSTD2 serves as a marker of poor prognosis in various solid tumours, such as breast, ovarian, prostate, hepatocellular, and oral squamous cell carcinomas." (PMID 41331197, 2025).
glioma (8 papers, 2015 to 2025). A benign or malignant brain and spinal cord tumor that arises from glial cells (astrocytes, oligodendrocytes, ependymal cells). "Similarly, expression of the TGFβ1 response gene, TACSTD2 (or TROP2), in cancer tissue (e.g., human glioma) has been shown to correlate with microvessel density—a commonly used marker for estimation of angiogenesis." (PMID 38132326, 2023).
head and neck cancer (8 papers, 2014 to 2025). A primary or metastatic malignant neoplasm affecting the head and neck. "Tumor-associated calcium signal transducer 2 (TACSTD2), a cell-surface glycoprotein, has been reported to be overexpressed in most epithelial tumors and was validated as miR-125b target in head and neck cancer." (PMID 24774301, 2014).
melanoma (8 papers, 2004 to 2026). A malignant, usually aggressive tumor composed of atypical, neoplastic melanocytes. "In contrast, melanoma cells of the dermal compartment had significantly lower expression of TACSTD2 and LGALS7, amongst others." (PMID 37602975, 2023).